PTOV1 (PTOV1 extended AT-hook containing adaptor protein)
Diseases named in the same sentence as PTOV1 in open-access papers (continued):
Sharing a sentence is not in itself a finding about the gene and the disease.
breast carcinoma (continued). "Thus, PTOV1 may be a useful marker for determining prognosis and guiding the follow-up schedule of breast cancer patients." (PMID 24947166, 2014). "Thus, PTOV1 protein expression might be a useful marker for stratifying breast cancer patientsprognosis as well as an effective novel criteria for selection of therapeutic options." (PMID 24947166, 2014). "Therefore, we speculated that PTOV1 might promote breast cancer tumorigenesis through the transcription factor c-Jun and its downstream genes." (PMID 24947166, 2014). "Overexpression of PIN1 increases the PTOV1 expression as a novel interactome of PIN1, and knockdown of both genes inhibits the expression of β-catenin, cyclin D1, and c-Myc in breast cancer MDA-MB-231 cells." (PMID 39202474, 2024). "It was previously reported that PTOV1 cloud impaired the expression of DKK1, a negative regulator of β-catenin, to activate β-catenin signaling in breast cancer." (PMID 31387622, 2019). "PTOV1 is a transcriptional repressor of the DKK1 gene, an action that triggers the activation of the Wnt/β-catenin signaling and tumor progression in breast cancer cells, and of the retinoic acid receptor (RARβ), favoring cell resistance to retinoic acid." (PMID 28938627, 2017). "Thus, we assumed that PTOV1 might promote breast cancer progression through a similar mechanism." (PMID 24947166, 2014). "The purpose of our study was to reveal how PTOV1 and PIN1 coordinate to drive breast cancer progression, towards this end we used siRNA silencing approach to find out the change in expression profile of various oncogenic signal molecules at transcription and translation levels in MDA-MB-231 cells." (PMID 31083670, 2019). "PTOV1 was markedly upregulated at both the protein and mRNA levels in all eight human primary breast cancer samples compared with the matched adjacent noncancerous breast tissues." (PMID 24947166, 2014). "However, the expression and clinical relevance of PTOV1 in breast cancer have not been determined." (PMID 24947166, 2014).
prostate tumors (5 papers, 2014 to 2021). "In prostate tumors, the overexpression of PTOV1 was associated with decreased expression of HEY1 and HES1, and this correlation was significant in metastatic lesions." (PMID 24684754, 2014). "These analyses reveal that primary prostate tumors show significantly higher expression of PTOV1, CCNG2 and MYC compared to benign tissue (GSE29079), and PTOV1 levels significantly correlate with CCNG2 and MYC mRNA levels." (PMID 28938627, 2017). "We have shown that PTOV1 in metastatic prostate tumors is significantly overexpressed and represses the transcription of the downstream targets of Notch, the HES1 and HEY1 genes, by interacting with SMRT, RBP-Jκ, NCoR, HDAC1 and HDAC4." (PMID 28029646, 2017). "In aggressive prostate tumors, PTOV1 stained intensely in the nucleus of local and distal (bones) metastatic cells." (PMID 28029646, 2017). "Analyses of tumor datasets show that PTOV1 expression significantly correlated with prostate tumor grade, drug resistance (CCNG2) and self-renewal (ALDH1A1, MYC) markers." (PMID 28938627, 2017). "An important contribution to higher levels of PTOV1 in prostate tumors is given by the frequent rate of gene amplifications, also found in other tumor types." (PMID 28029646, 2017). "High levels of PTOV1 in prostatic tumors also correlated significantly with the Ki-67 proliferative index and its nuclear localization, suggesting a functional relationship between PTOV1 overexpression, proliferative status and nuclear localization." (PMID 26992242, 2016). "High levels of PTOV1 in prostatic tumors correlate with the Ki67 proliferative index, indicating that increased PTOV1 expression is functionally related to the cells' proliferative status." (PMID 26992242, 2016). "In prostate tumors, the reciprocal expression patterns observed for PTOV1 and Notch targets support our in vitro findings." (PMID 24684754, 2014). "The significant increased expression of PTOV1 in primary prostate tumors may be predictor of metastastatic progression." (PMID 28938627, 2017). "An important contribution to higher levels of PTOV1 in aggressive prostate tumors might be given by the high rate of PTOV1 amplifications, also found in other tumor types, as shown by analyses of publicly available genomic datasets." (PMID 28029646, 2017). "Prostate Tumor Overexpressed-1 (PTOV1) was first described as gene and protein overexpressed in prostate tumors and preneoplastic lesions of high grade intraepithelial neoplasia (HGPIN)." (PMID 28029646, 2017). "Our study identifies PTOV1, ALDH1A1 and CCNG2 as potential markers of metastasis and bad prognosis when detected in primary prostate tumors." (PMID 28938627, 2017).
lymph node metastasis (3 papers, 2014 to 2016). "Moreover, the MOD values of PTOV1 staining were markedly higher in the lymph node metastasis group than in the lymph node metastasis-free group (P < 0.001)." (PMID 26992242, 2016). "We also suggest that determining PTOV1 expression levels may help to detect early lymph node metastasis of NPC patients, permitting the stratification of patients for the selection of treatments." (PMID 26305455, 2015). "Similarly, patients with higher PTOV1 expression level had significantly shorter survival time in groups of: pT1-2 (P < 0.001), lymph node metastasis positive (including: pN1, pN2 and pN3) (P < 0.001) and pM0 (P < 0.001)." (PMID 24947166, 2014). "Thus, the upregulation of PTOV1 could aid in detecting early lymph node metastasis of NPC patients and guiding their follow-up schedule." (PMID 26305455, 2015). "Hence, PTOV1 may help to detect early lymph node metastasis of NPC patients and serve as an independent prognostic biomarker for human NPC." (PMID 26305455, 2015). "Therefore, testing the PTOV1 protein level may help to detect early lymph node metastasis of NPC patients and serve as an independent prognostic biomarker for human NPC." (PMID 26305455, 2015).
bladder cancers (2 papers, 2014 to 2016). "Subsequently, the role of PTOV-1 overexpression in the proliferative status of tumor cells has been implicated in other neoplasms, such as breast, ovary and bladder cancers." (PMID 26992242, 2016). "The nuclear localization of PTOV1 was previously associated with higher proliferative index and tumor grade, suggesting a link between nuclear PTOV1 and cancer progression in different tumor types, including prostate and bladder cancers." (PMID 24684754, 2014).
laryngeal carcinoma (2 papers, 2016 to 2020). Carcinoma that arises from the laryngeal epithelium. "Expression of PTOV1 induces autophagy and is associated with increased resistance to cisplatin in vitro and in laryngeal cancer patients." (PMID 32878084, 2020). "However, while this study offers some preliminary data on a role for PTOV-1 in laryngeal carcinoma, the underlying molecular mechanisms of PTOV-1 in LSCC development and progression require further investigation." (PMID 26992242, 2016).
laryngeal squamous cell carcinoma (2 papers, 2016 to 2017). A squamous cell carcinoma that arises from the larynx. "In laryngeal squamous cell carcinoma, PTOV1 expression correlates with advanced clinical stage and it was shown to be an independent predictor of overall survival and progression-free survival." (PMID 28029646, 2017). "In this context, the levels of expression of PTOV1 in combination with the infection status with the human papillomavirus (HPV) could predict outcome in early-stage laryngeal squamous cell carcinoma." (PMID 28029646, 2017).
lung adenocarcinoma (2 papers, 2019 to 2025). A carcinoma that arises from the lung and is characterized by the presence of malignant glandular epithelial cells. "Data from the TCGA database also showed that PTOV1 levels were dramatically increased in both lung adenocarcinoma (LUAD) and lung squamous cell carcinoma (LUSC) tissues as compared to the normal control." (PMID 31387622, 2019). "In the TCGA lung adenocarcinoma cohort, PPP2R1A expression demonstrated significant positively correlated with PRPF31 (R = 0.72), SCAF1 (R = 0.72), and PTOV1 (R = 0.71)." (PMID 41409293, 2025).
nasopharyngeal carcinoma (2 papers, 2015 to 2021). A carcinoma arising from the nasopharyngeal epithelium. "Many reports have observed the chemically-induced behavior of nasopharyngeal carcinoma cells; therefore, drug resistance regulated by PTOV1 represents attractive target for NPC therapy." (PMID 26305455, 2015). "However, the clinical significance of PTOV1 in the development and progression of nasopharyngeal carcinoma (NPC) is unclear." (PMID 26305455, 2015). "However, our findings confirmed that PTOV1 is overexpressed in nasopharyngeal carcinoma and may act as a novel predictor for prognosis and survival of NPC patients." (PMID 26305455, 2015).
non-small cell lung carcinoma (2 papers, 2015 to 2019). A group of at least three distinct histological types of lung cancer, including non-small cell squamous cell carcinoma, adenocarcinoma, and large cell carcinoma. "Recent publications reported that PTOV1 cooperates with Zyxin in retinoic acid receptor (RAR) repression by abolishing the binding of the RAR coactivator CBP to the RAR target in non-small-cell lung cancer cells." (PMID 26305455, 2015). "However, the clinical significance and biological role of PTOV1 remain elusive in non-small cell lung cancer (NSCLC)." (PMID 31387622, 2019).
prostate adenocarcinoma (2 papers, 2014 to 2017). "To know the relative contributions of PTOV1 and Notch signaling to malignancy in PC, we analyzed the expression of PTOV1, HEY1 and HES1 in 45 prostate adenocarcinomas and control associated benign peripheral zone (BPZ) by real-time RT-PCR." (PMID 24684754, 2014). "ALDH1A1, PTOV1 and CCNG2 transcripts levels are also significantly higher in primary prostatic adenocarcinomas of patients that after radical prostatectomy developed regional or distal metastasis, suggesting their relationship with metastatic progression." (PMID 28938627, 2017).
lung carcinoma (1 paper, 2019). "Additionally, our results showed that depleting PTOV1 sensitizes lung cancer cell lines to chemotherapeutic drugs, cisplatin and docetaxel in vitro and in vivo, through attenuating cancer stem cell traits." (PMID 31387622, 2019). "However, the significance of PTOV1 expression in lung cancer has not been studied." (PMID 31387622, 2019).
lupus erythematosus (1 paper, 2025). An autoimmune, connective tissue chronic inflammatory disorder affecting the skin, joints, kidneys, lungs, heart, and the peripheral blood cells. "For instance, FAM71E1 and EMC10 have been associated with lupus erythematosus and genes like PGA3, VWCE, and PTOV1 are associated with immune infiltrates and immunity in various tumors." (PMID 41009814, 2025).
metastatic tumors (1 paper, 2016). "Moreover, overexpression of PTOV1 in primary and metastatic tumors significantly increases the translation of active c-Jun and its nuclear localization." (PMID 26992242, 2016).
cancer (11 papers, 2014 to 2026). A tumor composed of atypical neoplastic, often pleomorphic cells that invade other tissues. "In view of all these situations, there is paid new attention to reveal the prognostic value and clinicopathological association of PTOV1 abnormal expression in cancers." (PMID 34918668, 2021). "This higher expression in HGPIN was found helpful to discriminate those premalignant lesions associated with cancer, suggesting the potential value of PTOV1 detection in the early diagnosis of PC." (PMID 28029646, 2017). "The study will provide updated evidence to assess whether the expression of PTOV1 is in association with poor prognosis in patients with cancers." (PMID 34918668, 2021). "In addition, a significant association between high levels of PTOV1 and unfavorable prognosis and poor survival has been observed in several types of carcinomas." (PMID 28029646, 2017). "Recently, people have paid recent attention to the oncogenic PTOV1 protein as a regulator with various cellular functions and pathways that tend to enhance cell growth and self-renewal in numerous cancer cell types." (PMID 34918668, 2021). "Significant overexpression of PTOV1 has been suggested to exhibit an anti-cancer effect when knockdown." (PMID 33888815, 2021). "Our study verified that depleting PTOV1 attenuated cancer stem cell traits through impairing DKK1/β-catenin signaling to enhance chemosensitivity of NSCLC cells." (PMID 31387622, 2019). "Together, these findings suggest that PTOV1 regulates chemosensitivity in malignant tumors and depleting PTOV1 chemosensitizes NSCLC cells." (PMID 31387622, 2019). "Prostate tumor over expressed gene 1 (PTOV1) has been reported as an oncogene in several human cancers." (PMID 31387622, 2019). "The data are used to formulate a model for the mechanisms of action of PTOV1 in line with its recently described activities and cellular pathways modulated in cancer." (PMID 28029646, 2017). "Here, we will focus on the role of PTOV1 in cancer, re-examine its pro-oncogenic effects and re-evaluate the most relevant interactions and evidences of its cellular functions." (PMID 28029646, 2017). "The numerous evidences that PTOV1 is expressed significantly more in aggressive tumors and metastatic lesions and its implication in the mechanisms leading to cancer progression, suggested a potential action of this protein in recurrence." (PMID 28029646, 2017). "These proteins are involved in several cellular processes, although it is not clear how each interaction contributes to a role of dysregulated PTOV1 expression in cancer progression." (PMID 28029646, 2017). "More recently, the expression of PTOV1 in atypical adenomatous hyperplasia (AAH), a proliferative lesion of the transition zone of the prostate that morphologically resembles low grade carcinoma, has been associated with PC." (PMID 28029646, 2017). "Prostate tumor overexpressed 1 (PTOV1) has been reported to contribute to increased cancer proliferation." (PMID 26305455, 2015). "Recently, PTOV1 was shown to cooperate with Zyxin to reduce retinoic acid (RA) sensitivity, which is critical for cancer therapy with retinoids." (PMID 26305455, 2015). "Prostate tumor overexpressed 1 (PTOV1) was demonstrated to play an important role in cancer progression and was correlated with unfavorable clinical outcome." (PMID 24947166, 2014). "We thus searched for interactions of PTOV1 with transcriptional networks known to participate in the progression of PC and other cancers." (PMID 24684754, 2014). "PTOV1 expression is elevated in multiple cancers, including lung, endometrium, bladder, kidney and ovary cancer." (PMID 24947166, 2014).
cancer (continued). "The subcellular location of PTOV1 was mainly in the cytoplasm of primary cancer cells, which is consistent with previous reports." (PMID 24947166, 2014). "We found that PIN1 and PTOV1 both hold promising target to change the redox status of cancer cells." (PMID 31083670, 2019). "Of interest, the proportions of Ki-67 positive nuclei and the levels of PTOV1 in HGPIN areas adjacent to cancer lesions are higher than those found in HGPIN areas away from the cancer, supporting the concept of field cancerization or field effect in prostatic carcinogenesis." (PMID 28029646, 2017). "As expected, PTOV1 expression was significantly higher in cancer with respect to BPZ." (PMID 24684754, 2014). "Although it is difficult to ascertain how each of these interactions contributes to a possible role of dysregulated PTOV1 expression in cancer progression, this protein modulates cell proliferation, cell cycle progression, protein synthesis and gene transcription." (PMID 24684754, 2014). "Taken together, these results confirmed that overexpression of PTOV1 could contribute to the proliferative status of tumor cells, indicating that PTOV1 is involved in the progression of cancer." (PMID 24947166, 2014). "In contrast, the expression of HEY1 followed a pattern almost reciprocal to that of PTOV1 and it was significantly stronger in epithelial cells in BPZ and pre-malignant HGPIN compared to cancer and metastasis, confirming the results at the mRNA level." (PMID 24684754, 2014). "However, the clinical role of PTOV1 in cancer remains largely unknown." (PMID 24947166, 2014). "The Cancer Genome Atlas (TCGA) data and NCBI/GEO data mining, western blotting analysis and immunohistochemistry were employed to characterize the expression of PTOV1 in NSCLC cell lines and tissues." (PMID 31387622, 2019). "As high expression of PTOV1 predicting poor prognosis in NSCLC and the reported oncogenic roles of PTOV1 in types of cancer, we presumed that depletion of PTOV1 might benefit NSCLC treatment." (PMID 31387622, 2019). "PTOV1 was reported to be upregulated in kinds of cancer, however there is no systematic analysis of the expression of PTOV1 in NSCLC." (PMID 31387622, 2019).